BDNF (brain derived neurotrophic factor)
Diseases named in the same sentence as BDNF in open-access papers (continued):
Sharing a sentence is not in itself a finding about the gene and the disease.
insomnia (continued). "Furthermore, acupuncture has been shown to significantly increase serum BDNF levels in patients with insomnia." (PMID 40177248, 2025). "In our previous work on an insomnia rat model, several serum biochemical parameters were significantly changed, such as BDNF and GFAP; the concentration of several neurotransmitters in the brain was also different after the application of HWD, including GABA, 5-HT, and glutamate." (PMID 38846089, 2024). "In addition, warming needle moxibustion upregulated the transcript levels of brain-derived neurotrophic factor (BDNF), recombinant early growth response protein 1, and b-cell translocation gene 2, protecting the brain from insomnia-related damage." (PMID 39534607, 2024). "The neurobiological underpinnings of both OSA and insomnia involve complex interactions among various neuromodulators, including brain-derived neurotrophic factor (BDNF), its precursor proBDNF, glial-cell-line-derived neurotrophic factor (GDNF), neurotrophin-3 (NTF3), and neurotrophin-4 (NTF4)." (PMID 39126038, 2024). "Additionally, to our knowledge, this is the first study to evaluate the relationship between BDNF mRNA expression and insomnia symptoms." (PMID 38337587, 2024). "Specifically, patients experiencing insomnia have been found to have lower BDNF levels." (PMID 39767653, 2024). "Nowadays, it is well known that insomnia influences, in part, BDNF levels." (PMID 37108547, 2023). "The present study is an exploratory analysis that points to the relevance of targeting insomnia in the health and the cognitive state of older adults, since, according to our results, insomnia impacts BDNF concentration independently from clinical or sociodemographic variables." (PMID 37108547, 2023). "Overall, understudied with unclear results, BDNF may be related to sleep continuity and architecture that may contribute to the experience of disrupted and non‐restorative sleep in patients with insomnia." (PMID 36737401, 2023). "Interestingly, mRNA BDNF ratio pre/post therapy was negatively correlated with the severity of insomnia symptoms (AIS score) at the baseline (r = −0.409, p = 0.042), poor sleep quality (r = −0.441, p = 0.027)." (PMID 36984890, 2023). "Moreover, OSA subjects with more pronounced insomnia symptoms and impaired sleep quality were shown to have lower evening level of serum BDNF and proBDNF." (PMID 36984890, 2023). "In addition, several studies have reported decreased BDNF in patients with chronic stress or insomnia." (PMID 37075032, 2023). "In conclusion, BDNF levels may be useful in defining the insomnia phenotype in patients with OSA characterized by excessive daytime sleepiness." (PMID 36498709, 2022). "Higher BDNF levels may define OSA phenotypes with comorbid insomnia, provide a better description of this heterogenic disorder, and further support proper treatment decisions." (PMID 36498709, 2022). "Down-regulation of BDNF in insomnia could be explained by hyperactivity of the stress response system and inflammation." (PMID 36498709, 2022). "In the last few years, it has been hypothesized that BDNF level is related to depression, sleep, and insomnia." (PMID 34807519, 2021). "However, in addition to reduced BDNF levels due to insomnia, wakefulness gave during SD, as an acute stressor for the brain, cause an increase in BDNF content." (PMID 33023629, 2020). "Although the role of myokine on the pathophysiology of sarcopenia remains unclear, it is hypothesized that the low level of irisin induces a decrease in BDNF synthesis and is related to the pathophysiology of insomnia in sarcopenia." (PMID 32723368, 2020). "Maintenance of sleep homeostatic autoregulation in rats with selective sleep deprivation during rapid eye movement sleep is associated with increased levels of BDNF in the body (Datta, Knapp, Koultiwari, & Barnes, 2015), confirming the improvement of insomnia symptoms by BDNF." (PMID 30609300, 2019).
insomnia (continued). "Later work revealed that PA-induced reductions in hypersomnia were positively correlated with reductions in BDNF and IL-1β, a trend that was not present in those with insomnia, suggesting differential biomarker associations for hypersomnia and insomnia." (PMID 28529805, 2017). "As previously shown, insomnia was correlated with decreased serum BDNF levels." (PMID 24146812, 2013). "Recently, we could demonstrate that subjects suffering from current symptoms of insomnia exhibited significantly decreased serum BDNF levels compared with sleep-healthy controls." (PMID 24146812, 2013). "Of note, an association between the PSS and BDNF was only observed in subjects with no insomnia (rp = −0.511, p = 0.013) compared to subjects with sub threshold (rp = 0.069, p = 0.814) or clinical insomnia (rp = 0.199, p = 0.608)." (PMID 24146812, 2013). "We found a significant interaction between stress and insomnia with an impact on serum BDNF levels." (PMID 24146812, 2013). "Additionally, BDNF and NGF concentrations were significantly augmented in the observation group, emphasizing the therapeutic potency of the formula for IS patients experiencing insomnia due to qi deficiency and blood stasis." (PMID 40760550, 2025). "The onset of insomnia could be associated with certain neurotransmitters, like γ-aminobutyric acid (GABA), 5-hydroxytryptamine (5-HT), and brain-derived neurotrophic factor (BDNF)." (PMID 38675375, 2024). "Moreover, in this group, the BDNF level was correlated with the severity of insomnia." (PMID 36294343, 2022). "The role of stress on the structure of neuroplasticity, such as the release of endocannabinoids and brain-derived neurotrophic factor (BDNF), could lead to restored sleep and improvement of insomnia but also lead to sleep deprivation, which may have an effect on sleep." (PMID 33401720, 2021). "Of note, the association between stress and BDNF was only observed in subjects without insomnia." (PMID 24146812, 2013). "Furthermore, research has identified a strong association between insomnia and the dysregulation of monoamine and amino acid neurotransmitters within the central nervous system, with significant reductions in 5-HT, GABA, and BDNF levels observed in insomniac mice." (PMID 41011145, 2025). "Additionally, our results from the linear analysis demonstrate that insomnia is associated with a decreased BDNF concentration in the serum of older adults, independent of the cognitive status, suggesting that sleep disturbances such as insomnia exert a significant influence on this neurotrophin." (PMID 37108547, 2023). "One of the proposed mechanisms by which insomnia may trigger the development of AD is through decreased clearance of amyloid beta by astrocytes, aggregation of tau proteins, decreased production of the brain-derived neurotrophic factor (BDNF), and the development of inflammatory responses." (PMID 37489355, 2023). "In this study, we demonstrated increased evening levels of BDNF and proBDNF in patients with OSA who scored high on questionnaires assessing poor sleep quality and insomnia symptoms (PSQI and AIS, respectively)." (PMID 36498709, 2022). "They completed questionnaires on sleep (ISI, Insomnia Severity Index) and stress (PSS, Perceived Stress Scale) and provided a blood sample for determination of serum BDNF." (PMID 24146812, 2013). "To further elucidate the complex interplay between stress, insomnia and BDNF we calculated an ANCOVA (BDNF as dependent variable, insomnia and stress as independent variables and smoking as co-variable)." (PMID 24146812, 2013). "Lower levels of irisin, BDNF and meteorin, and higher levels of FGF-21 and interleukins 6 and 10, lead to sleep disturbances, like insomnia, reduction of REM (rapid eye movement) sleep time and lower slow-wave activity during the NREM (non-rapid eye movement) sleep phase." (PMID 41010737, 2025). "It has been shown that it is not insomnia itself, but a short sleep duration that reduces BDNF levels." (PMID 38337587, 2024).
insomnia (continued). "A different study found a negative correlation between BDNF and the severity of insomnia symptoms, as measured by the Insomnia Severity Index." (PMID 38337587, 2024). "The results indicated that PC extract and NADA could effectively ameliorate hypothalamic pathology of insomnia rats, increase the levels of 5-HT, GABA, and BDNF, and decrease the levels of DA, DOPAC, and HVA." (PMID 39125043, 2024). "According to some results found, changes in BDNF concentration are followed by a reduction in insomnia and its consequences, rather than the improvement of depressive symptoms." (PMID 29299044, 2017). "Moreover, insomnia severity groups and score on the PSS each revealed a significant main effect on serum BDNF levels." (PMID 24146812, 2013). "Serum BDNF levels in the group with no insomnia were significantly higher compared to the groups reporting sub threshold and clinical insomnia." (PMID 24146812, 2013). "Therefore, PC extract and NADA might ameliorate insomnia in rats by affecting 5-HT, GABA, and DA levels and 5-HT1A, BDNF, and DARPP-32 protein expression." (PMID 39125043, 2024). "However, it must be mentioned that individuals with no clinically significant insomnia had higher expression levels of BDNF and NTF3 in the OSA group compared to controls." (PMID 39126038, 2024). "However, this preliminary study did not examine which specific insomnia symptoms specifically affect BDNF levels." (PMID 38337587, 2024). "However, serum BDNF in middle‐aged adults with insomnia appears to be a biomarker only for insomnia complaints, but not for objectively assessed poor sleep continuity." (PMID 36737401, 2023). "Except for a correlation between BDNF and sleep efficiency in IBD subjects, none of the associations of measured sleep parameters (sleep latency, daytime sleepiness, sleep quality, total sleep time, symptoms of insomnia) was significant." (PMID 36984890, 2023). "Although the direction of this association resembles the BDNF alterations observed in MDD, the present study could not verify a potential contribution of insomnia to neurotrophic abnormalities in a clinical sample." (PMID 37176140, 2023). "The potential correlation between the BDNF levels, interleukin-6 (IL-6), tumour necrosis factor-alpha (TNF-α), and depressive symptoms such as nine-item patient health questionnaire (PHQ-9) and Athens insomnia scale (AIS) were evaluated with multivariate logistic regression analysis." (PMID 31234814, 2019). "It is important to mention that level of BDNF is not a single determinant of how severely individuals rate their pain; increased sensitivity to nociceptive stimuli might also occur in conditions where BDNF is decreased, such as insomnia." (PMID 36768132, 2023).
amyotrophic lateral sclerosis (78 papers, 2010 to 2025). Amyotrophic lateral sclerosis (ALS) is a neurodegenerative disease characterized by progressive muscular paralysis reflecting degeneration of motor neurons in the primary motor cortex, corticospinal tracts, brainstem and spinal cord. "BDNF rs56164415 polymorphism was also associated with other neurodegenerative disorders, such as amyotrophic lateral sclerosis, where the frequency of the CT genotype and T allele was higher in the patient group of the Han Chinese origin than in controls." (PMID 33926045, 2021). "BDNF, coding for Brain-Derived Neurotrophic Factor, is a gene that has previously been implicated in PD, and BDNF has been discussed as a potential therapeutic agent in neurodegenerative disease but has previously been unsuccessful in clinical trials in patients with amyotrophic lateral sclerosis." (PMID 28609445, 2017). "In a clinical trial of amyotrophic lateral sclerosis, recombinant human BDNF was administered by subcutaneous (SC) administration." (PMID 38035276, 2023). "Over 25 years ago, a clinical trial in amyotrophic lateral sclerosis (ALS) investigated the therapeutic effects of chronic treatment with BDNF, where the neurotrophin was administered by SQ injection." (PMID 37583474, 2023). "In line with this, BDNF-dependent axonal transport has been found to be defective in the mouse model of amyotrophic lateral sclerosis SOD1." (PMID 37445838, 2023). "An earlier clinical trial demonstrated increased BDNF levels within the cerebrospinal fluid following intrathecal administration of recombinant BDNF in patients with amyotrophic lateral sclerosis (ALS)." (PMID 35283994, 2022). "The peripheral application of BDNF increased heart rate in patients with amyotrophic lateral sclerosis, and intracerebroventricular administration of BDNF increased heart rate in mice." (PMID 34202148, 2021). "Unfortunately, the outcomes of several clinical trials involved the intrathecal infusion of recombinant BDNF to treat patients with amyotrophic lateral sclerosis have been disappointing due to the short in vivo half-life and poor delivery of BDNF." (PMID 33029123, 2020). "Evidence suggests that alterations in BDNF/TrkB, including TrkB transactivation by A2aRs, can occur in several neurodegenerative diseases, including amyotrophic lateral sclerosis (ALS)." (PMID 31456666, 2019). "For instance, hind limb muscles of amyotrophic lateral sclerosis mouse models display a significant decline in the number of NMJs expressing BDNF, NT-4, GDNF, p75NTR, TrkB, and TrkC." (PMID 31514753, 2019). "Moreover, PKA collaborates with PKC to regulate ACh release at the NMJ, and PKA has been associated with BDNF/TrkB retrograde signalling during NMJ development and in amyotrophic lateral sclerosis (ALS) disease." (PMID 39044222, 2024). "BDNF crosses the blood-brain barrier only in minimal amounts, making peripheral administration inadequate for treatment, as seen in a large clinical trial seeking to treat amyotrophic lateral sclerosis (ALS)." (PMID 28273811, 2017). "Spinal muscular atrophy (SMA) and amyotrophic lateral sclerosis (ALS) are other common forms of motor neuropathies, and BDNF has been suggested as being a possible therapeutic option." (PMID 39200370, 2024). "Enhancement of BDNF levels has been considered one of the main strategies to stop or prolong the progression of amyotrophic lateral sclerosis (ALS)." (PMID 35916975, 2022). "The first clinical trials that investigated the effect of BDNF administration in neurodegenerative diseases were performed in patients with amyotrophic lateral sclerosis (ALS)." (PMID 32050617, 2020). "If any, the p75NTR protein fragments expressed by p75NTR exon III null mice could play a beneficial effect in the context of the NMJ, as they have been shown to increase BDNF-TrkB dependent survival of motor neurons in vitro and in vivo in the hSODG93A mice model of amyotrophic lateral sclerosis." (PMID 31514753, 2019).
amyotrophic lateral sclerosis (continued). "Furthermore, in amyotrophic lateral sclerosis, the brain-derived neurotrophic factor (BDNF) production may play a role by regulating with neuronal activity by rTMS in primary motor cortex." (PMID 29867712, 2018). "A recent study showed a significant up-regulation of MEF2C and MEF2D mRNA levels in both sporadic and SOD1+ amyotrophic lateral sclerosis (ALS) patients detected by gene expression analysis, and a down-regulation of their targets, BDNF, KLF6, and RUFY3." (PMID 29340119, 2017). "In addition, basal more than BDNF-dependent TrkB activity may play a critical role in the etiology of some pathologies such as epileptogenesis, amyotrophic lateral sclerosis and cancer metastases." (PMID 20333308, 2010). "The stimulation of motor neurons with BDNF may improve motor function in an amyotrophic lateral sclerosis (ALS) model." (PMID 37299526, 2023). "The discovery of muscle-derived BDNF as an inductor of sprouting after partial deafferentation could, then, be thought of as a potential therapy to stop, or at least delay, spinal motoneuron death, as has already been shown in murine models of amyotrophic lateral sclerosis." (PMID 37445838, 2023). "In amyotrophic lateral sclerosis (ALS), BDNF has long been a drug candidate." (PMID 32403409, 2020). "Strikingly, in another human disease of progressive neuronal death, amyotrophic lateral sclerosis (ALS or Lou Gehrig's Disease), intravenous infusions of BDNF were shown to improve the respiratory capabilities of late-stage patients." (PMID 22363780, 2012). "Interestingly, BDNF signaling through inhibition of oxidative stress prevents glutamate-induced neurotoxicity in PD and the final phase of amyotrophic lateral sclerosis (ALS)." (PMID 40380033, 2025). "For example, transplantation of BDNF-overexpressing hUC-MSC-derived motor neurons could improve motor performance and prolong the survival of the amyotrophic lateral sclerosis (ALS) model in mice." (PMID 35393444, 2022). "For example, GDNF-fragment C promotes neuronal survival and neurite outgrowth in animal models of Parkinson’s disease and amyotrophic lateral sclerosis (ALS), and BDNF-fragment C is protective in a mouse model of ALS, although no synergistic effect of this recombinant molecule was found." (PMID 22837670, 2012). "BDNF and GDNF have been long described as major regulators of survival, maintenance and regeneration of specific neuronal populations in the adult brain, so as to be considered valuable therapeutic options for various neurodegenerative diseases, including amyotrophic lateral sclerosis (ALS)." (PMID 30210286, 2018). "In line with this hypothesis, low frequency rTMS applied to the prefrontal cortex may induce a decrease in BDNF levels in healthy volunteers but not in patients with amyotrophic lateral sclerosis, who showed a decrease in BDNF levels only after high-frequency rTMS." (PMID 34069556, 2021). "For instance, in a phase III clinical trial for the treatment of amyotrophic lateral sclerosis (ALS), a daily subcutaneous administration of BDNF offered no clinical benefit." (PMID 23320097, 2013). "Despite promising outcomes from select research conducted in preclinical animal models, a large-scale clinical trial involving oral BDNF supplementation in patients with amyotrophic lateral sclerosis (ALS) did not significantly increase patient survival at dosages of 50–100 mg/day." (PMID 35887357, 2022). "BDNF is reported to slow the progression of motor neuron atrophy in an animal model of amyotrophic lateral sclerosis (ALS), and the TrkB agonist 7,8-dihydroxyflavone (7,8-DHF) improved motor neuron deficits in the superoxide dismutase 1 (SOD1G93A) ALS mouse models." (PMID 34833132, 2021). "However, in clinical trials, BDNF has failed to benefit patients with amyotrophic lateral sclerosis (ALS)." (PMID 22761934, 2012).